USP36 (ubiquitin specific peptidase 36)
Diseases named in the same sentence as USP36 in open-access papers (continued):
Sharing a sentence is not in itself a finding about the gene and the disease.
cancer (14 papers, 2020 to 2026). A tumor composed of atypical neoplastic, often pleomorphic cells that invade other tissues. "This review underscores the importance of comprehending the protein interactions of USP36, particularly in the context of their implications for cancer and other biological processes." (PMID 38785979, 2024). "The summarized information regarding the function, expression, and targets of USP36 in various cancers provides a comprehensive resource for understanding the role of USP36 in different pathological conditions." (PMID 38785979, 2024). "Based on the molecular docking analysis, CBF, a potential drug against other cancers, was identified to interact with the catalytic domain of USP36." (PMID 38517383, 2024). "Subsequent research efforts should therefore prioritize the investigation of oncogenic mechanisms through which USP36 operates in HCC, independently validating the reported observations regarding the involvement of USP36 in this specific type of cancer." (PMID 38785979, 2024). "One highlight of this study is that USP36-mediated stabilization of nucleolar Snail1 is essential for ribosome biogenesis and cancer cell survival upon ribotoxic stress." (PMID 37833415, 2023). "Here, we report that USP36, a nucleolar ubiquitin-specific protease essential for ribosome biogenesis and cell growth and frequently overexpressed in cancer, acts as a novel posttranslational regulator of DGCR8." (PMID 36950067, 2023). "Since HHT promotes 47S pre-rRNA expression, we next examined the role of the nucleolar USP36-Snail1–47S pre-rRNA axis in the regulation of HHT-induced cancer cell apoptosis." (PMID 37833415, 2023). "The CCK-8 assay showed that USP36 depletion suppressed cancer cell proliferation in ECA109, KYSE150, and EC9706 cells." (PMID 36470870, 2022). "According to immunohistochemistry analysis of 107 samples, high USP36 protein expression was correlated with poor cancer differentiation (P = 0.007)." (PMID 36470870, 2022). "Propidium iodide (PI) staining coupled with Annexin V staining indicated that USP36 depletion facilitated cancer cell apoptosis in ECA109, KYSE150 and EC9706 cells." (PMID 36470870, 2022). "Overexpression of USP36 promotes cancer cell proliferation through deubiquitinating and stabilizing c-Myc protein in the nucleolus." (PMID 33237263, 2020). "Taken together, these data support an important role of USP36 in regulating the response of cancer cells to anti-cancer drugs through PrimPol stabilization." (PMID 33237263, 2020). "Our data confirm that USP36 is a novel regulator of cIAP1 and survivin and may represent a new therapeutic target for cancer treatment." (PMID 38876304, 2024). "Flow cytometry was performed to examine the effect of USP36 on cancer cell apoptosis." (PMID 38876304, 2024). "As USP36 is aberrantly overexpressed in various human cancers and is critical for ribosome biogenesis and cell growth, it may be a promising therapeutic target in cancer." (PMID 39356143, 2024). "We examined the role of USP36 in cell survival using two cancer cell lines, HCT 116 and HCT-8." (PMID 38876304, 2024). "As USP36 is frequently overexpressed in various human cancers, its role in miRNA biogenesis may be deregulated in cancer cells, especially those oncogenic miRNAs." (PMID 36950067, 2023). "Similarly, the knockdown of USP36 markedly sensitized cancer cells to HHT-induced cell death, which were effectively rescued by ectopic expression of Snail1WT but not Snail1K157R." (PMID 37833415, 2023). "As USP36 is frequently overexpressed in various human cancers, our study suggests that deregulated USP36-miRNA biogenesis pathway may contribute to tumorigenesis." (PMID 36950067, 2023). "Since we proved that USP36 is required for ESCC progression and Hippo/YAP activation, we carried out further rescue experiments to test whether USP36 modulates cancer progression through YAP." (PMID 36470870, 2022). "We further silenced USP36 in ECA109 cancer cells for RNA sequencing analysis." (PMID 36470870, 2022).
cancer (continued). "On the other hand, in cancer cells, higher expression of USP36 might render cancer cells resistant to replication stress, while lower USP36 level or inhibition of USP36-PrimPol axis might sensitize cancer cells to genotoxic insults." (PMID 33237263, 2020). "Our study reveals a novel mechanism governing PrimPol protein stability by USP36 in human cancers." (PMID 33237263, 2020). "Cancer cells generally have higher replication stress, and the USP36-PrimPol axis might be required to adapt to this stress." (PMID 33237263, 2020). "Thus, targeting USP36 may represent a potential therapeutic approach for attenuating the proliferation and survival of cancer cells." (PMID 38785979, 2024). "Moreover, USP36 has been shown to be overexpressed in multiple types of human cancers, and might have oncogenic activity." (PMID 33237263, 2020). "In addition, USP36 regulates cancer therapeutic resistance in a PrimPol-dependent manner." (PMID 33237263, 2020). "USP35, USP36, USP37, USP47, USP49, and OTUD6B play crucial roles in cancer progression and chemoresistance across various cancers, including NSCLC." (PMID 41399373, 2026). "The results showed that USP36 overexpressing HCT116 cells exerted stronger sphere-forming ability, which demonstrated the contributive role of USP36 in cancer stemness." (PMID 38517383, 2024). "Future work should aim to identify novel USP36 inhibitors targeting its DUB and SUMO ligase dual-enzyme activities for cancer treatment." (PMID 39356143, 2024). "These DUBs (USP22, USP28, USP29, USP36, USP37 and OTUD6A) are observed in stabilizing MYC in cancer cells." (PMID 36765885, 2023). "The reported deubiquitinases of MYC include USP22, USP28, USP29, USP36 and USP37, and they enhance cancer stemness via BMI1, LSD1 Snail and CEP63 stabilization, respectively." (PMID 36765885, 2023). "USP36, USP37, USP47, and OTUD6B exert its oncogenic effects by stabilizing key oncoproteins, such as cellular myelocytomatosis oncogene (c-Myc), 14-3-3γ, Snail, and β-catenin, thereby promoting cancer cell proliferation, migration, and invasion 27-32." (PMID 41399373, 2026). "Additionally, genes such as TSC2, FAM134C, USP36, TECPR1, and LRSAM1 are involved in pathways including macroautophagy and selective autophagy, which can contribute to cancer when dysregulated." (PMID 40279344, 2025). "Dysregulation of USP36 and its interaction with MYC may contribute to aberrant ribosome biogenesis and potentially drive cancer development." (PMID 38785979, 2024). "However, the knockdown of USP36-mediated cancer cell death upon ribotoxic stress can only be partly rescued by ectopic expression of wild-type Snail1, suggesting that Snail1 is important but not the only downstream effector of USP36." (PMID 37833415, 2023).
infection (2 papers, 2014 to 2023). The state of being infected such as from the introduction of a foreign agent such as serum, vaccine, antigenic substance or organism. "The D. melanogaster ubiquitin-specific protease 36 (USP36) and USP2 negatively regulate the IMD pathway after infection by Gram-negative pathogens." (PMID 36537797, 2023).
kidney (1 paper, 2024). "Conversely, work in the mouse and human kidney suggests that Usp36 interacts with SOD2 in the mechanism of acute kidney injury due to ischaemia." (PMID 38734725, 2024).
USP36 also shares sentences with these, for which no sentence is quoted: adenocarcinoma (1 paper); coronary artery disease (1); hepatocellular carcinoma (1); Hyperglycemia (1); Hypertension (1); leukemia (1); lymph node metastasis (1); migraine (1); nonalcoholic steatohepatitis (1); Obesity (1); prostate carcinoma (1); triple-negative breast carcinoma (1); type 2 diabetes (1).